ERBB4 (erb-b2 receptor tyrosine kinase 4)
Diseases named in the same sentence as ERBB4 in open-access papers (continued):
Sharing a sentence is not in itself a finding about the gene and the disease.
medulloblastoma (15 papers, 2012 to 2025). A malignant, invasive embryonal neoplasm arising from the cerebellum. "In most benign meningiomas, however, ErbB4 is underexpressed and co-expression of ErbB4 with ErbB2 has been associated with poor prognosis in medulloblastoma and with increased proliferation index in ependymomas." (PMID 36119496, 2022). "Strikingly, high ERBB4 expression was associated with shorter overall survival in Group 4 medulloblastomas (p = 1.8 × 10−3)." (PMID 32316671, 2020). "Translating these pre-clinical results to the clinic, ERBB4 expression is elevated in medulloblastoma samples where its high levels are associated with poor patient survival." (PMID 32316671, 2020). "Together, these analyses reveal advanced underlying molecular mechanisms of the activity of ERBB4 in medulloblastoma cells." (PMID 32316671, 2020). "However, analysis of ErbB4 isoform differential expression in medulloblastoma and ependymoma has highlighted the association between JM-a isoform expression and higher proliferative indices, translating to poorer survival rates." (PMID 36119496, 2022). "Taken together, our data depict a previously unknown role for ERBB4 as a central player of medulloblastoma biology, prognosis, and therapy, as well as reveal underlying molecular pathways for ERBB4 activity." (PMID 32316671, 2020). "In medulloblastoma, all ERBB4 variants are expressed, with JM-a and CYT-1 predominating." (PMID 30044378, 2018). "A paper by Zeng and colleagues analyzed the relative levels of the different JM and CYT isoforms of ERBB4 in two pediatric brain tumor types: highly malignant medulloblastoma and the relatively benign pilocytic astrocytoma." (PMID 36119496, 2022). "Overexpression of ErbB4 in conjunction with ErbB2 correlates with poor prognosis in medulloblastoma patients." (PMID 36119496, 2022). "Recent analysis of the relative RNA levels of ErbB4 isoforms has shed some light on the differential expression patterns present within medulloblastoma." (PMID 36119496, 2022). "ERBB4 is a tyrosine kinase receptor and is critical during cerebellum and medulloblastoma development, while SRC signaling controls important biological/oncogenic processes, including proliferation, apoptosis, cell adhesion and motility." (PMID 35011618, 2021). "Altogether, these results show that ERBB4 expression correlates with poor prognosis in all medulloblastomas groups, but it is especially elevated in Group 4 samples, where its high levels are a prognostic biomarker." (PMID 32316671, 2020). "When ERBB4 expression was analyzed in the different groups, its levels were higher in Group 4 medulloblastomas in all studied cohorts." (PMID 32316671, 2020). "We also found aberrant migration of CGNPs in ErbB4 mutant mice cerebella, in agreement with previous results, and also in medulloblastoma tumor cells." (PMID 32316671, 2020). "In medulloblastoma, it has been shown that human tumor samples express higher levels of ERBB4 than the healthy cerebellum, and that this high expression correlates with a poor prognosis." (PMID 32316671, 2020). "We found that Group 4 medulloblastomas presented the highest expression of ERBB4 in all the databases analyzed." (PMID 32316671, 2020). "We found that among the selected genes, three of the downregulated genes (BOC, VCAM1, and TP63) followed the same pattern as ERBB4 and showed a higher expression in Group 4 medulloblastomas." (PMID 32316671, 2020). "We also studied the expression of ERBB4 in several human medulloblastoma cell lines and detected higher levels in cells belonging to Group 4 (D283Med, D341Med, CHLA-01, and CHLA-01R) compared to DAOY and UW228 from the SHH subgroup." (PMID 32316671, 2020). "Our results show that ERBB4 plays a critical role for stem cell population in homeostasis during cerebellum development and also in pathological conditions in medulloblastoma." (PMID 32316671, 2020).
medulloblastoma (continued). "Altogether, these results showed that ERBB4 is required for medulloblastoma cell survival and hence tumor progression." (PMID 32316671, 2020). "Our data confirms that ERBB4 is also relevant for protecting CGNPs and medulloblastoma tumor cells from apoptosis in vitro and in vivo." (PMID 32316671, 2020). "For this, we analyzed the expression of ERBB4 in different databases of human clinical biopsies from medulloblastoma tumors." (PMID 32316671, 2020). "First, we compared the expression of ERBB4 in the four different established medulloblastoma groups." (PMID 32316671, 2020). "In this study, we characterized the role of ERBB4 during cerebellum development and medulloblastoma progression paying particular interests to its role in CGNPs and medulloblastoma stem cells (MBSCs)." (PMID 32316671, 2020). "All these results extrapolate the findings in vitro to clinical samples in vivo, and reveal several promising genes and pathways related to ERBB4 activity in medulloblastoma progression." (PMID 32316671, 2020). "Next, we crossed ErbB4 mutant mice with hGFAPcre;SmoM2 mice, which develop medulloblastoma spontaneously within 15–17 days after birth, and compared ErbB4 Het and KO mice." (PMID 32316671, 2020). "It was also reported that ERBB-2 and ERBB-4 are highly expressed in aggressive forms of medulloblastoma." (PMID 24986561, 2014). "Finally, we observed that ERBB4 knock-down resulted in a significant decrease in the migratory potential of medulloblastoma cells." (PMID 32316671, 2020). "Moreover, ErbB4 deletion in the medulloblastoma-prone SmoM2 mice also promotes apoptosis activation." (PMID 32316671, 2020). "Moreover, we reveal that ERBB4 is overexpressed in Group 4 medulloblastomas, the most common group, and that high expression levels of this receptor are associated with shorter overall patient survival." (PMID 32316671, 2020). "Finally, we identified and validated a set of 9 genes as downstream targets of ERBB4 activity in medulloblastoma." (PMID 32316671, 2020). "We investigated if ERBB4 plays a role in medulloblastoma progression." (PMID 32316671, 2020). "ERBB4 inhibition also increases tumor cells’ vulnerability prior to chemotherapy treatment in neuroblastoma and in lung cancer, but little is known about its role in cerebellar development and medulloblastoma." (PMID 32316671, 2020). "Next, we investigated the impact of ERBB4 in human medulloblastoma progression." (PMID 32316671, 2020). "Furthermore, we show that EGFR and ErbB2 are highly and ErbB3 and ErbB4 are hardly expressed on the cell surface of our medulloblastoma cell lines." (PMID 26496080, 2015). "Flow cytometry analysis revealed that MET (mean±sd: 74.9% ± 13.9%), EGFR (mean±sd: 77.4% ± 10.9%) and ErbB2 (mean±sd: 67.8% ± 10.3%) are highly expressed in all medulloblastoma cell lines, whereas ErbB3 (mean±sd: 4.0% ± 3.6%) and ErbB4 (mean±sd: 1.5% ± 2.1%) are barely expressed at all." (PMID 26496080, 2015). "Finally, we firmly established that ERBB4 behaves as an oncogene in medulloblastoma." (PMID 32316671, 2020). "In order to investigate the role of ERBB4 in MBSCs, we cultured two conventional DAOY and UW228 medulloblastoma cell lines, with low endogenous levels of ERBB4, and D283Med and D341Med, with high expression of the receptor, in the presence of serum and also in stem cell media to form oncospheres." (PMID 32316671, 2020).
pancreatic cancer (15 papers, 2013 to 2025). "By employing CRISPR/Cas9 gene‐editing technology we successfully deleted EGFR, ERBB2, ERBB3, and ERBB4, respectively, in the human pancreatic cancer cell line Panc‐1." (PMID 37341059, 2023). "Ectopic expression of miR-193b inhibits anchorage-independent growth by targeting ErbB4 in Ewing sarcoma and impairs the proliferation of pancreatic cancer cells through suppression of KRAS." (PMID 31262974, 2019). "We have previously demonstrated that in human pancreatic tumor cell lines in which the constitutively-active ErbB4 Q646C mutant functions as a tumor suppressor, wild-type ErbB4 appears to possess oncogenic activities." (PMID 24791013, 2013). "Among all subfamilies of RTKs, the ErbB family members consisting of the epidermal growth factor receptor EGFR (ErbB1), HER2 (ErbB2), HER3 (ErbB3), and HER4 (ErbB4) play important role in the initiation and maintenance of a variety of human cancers, including pancreatic cancer." (PMID 30961642, 2019). "ErbB4 mRNA level also correlates with pancreatic cancer with lymph node and distant metastases." (PMID 24348587, 2013). "Other studies showed that a constitutively active ERBB4 homodimer mutant inhibited colony formation in a pancreatic cancer cell line, and classified ERBB4 as a potential oncogene, after revealing enhanced anchorage‐independent growth of hPaCaCells by the stimulation of ectopic ERBB4 expression." (PMID 32335999, 2020). "Previous analyses of the constitutively-dimerized and –active ErbB4 Q646C mutant indicate that ErbB4 kinase activity and phosphorylation of ErbB4 Tyr1056 are both required for the tumor suppressor activity of this mutant in human breast, prostate, and pancreatic cancer cell lines." (PMID 24791013, 2013).
amyotrophic lateral sclerosis (12 papers, 2016 to 2025). Amyotrophic lateral sclerosis (ALS) is a neurodegenerative disease characterized by progressive muscular paralysis reflecting degeneration of motor neurons in the primary motor cortex, corticospinal tracts, brainstem and spinal cord. "Rare ERBB4 variants have been implicated in amyotrophic lateral sclerosis (ALS), but their prevalence and clinical significance remain poorly understood, particularly across different ethnic populations." (PMID 40469844, 2025). "On the other hand, the ERBB4 gene, or erb-b2 receptor tyrosine kinase 4, is involved in the pathogenesis of amyotrophic lateral sclerosis by a mutation that reduces autophosphorylation on ErbB4 upon neuregulin stimulation." (PMID 38788487, 2024). "Mutations in ErbB4 gene, encoding a member of the epidermal growth factor receptor, disrupt the Neuregulin-ErbB4 pathway, causing Amyotrophic Lateral Sclerosis (ALS), a neurodegenerative disease characterized by the loss of upper and lower motor neurons." (PMID 35409239, 2022). "The authors share the course of a patient with clinically established MSA-cerebellar type and lower motor neuron disease findings at par with progressive muscular atrophy (PMA), but tested positive for an ERBB4 gene mutation, which is linked to an amyotrophic lateral sclerosis (ALS) variant." (PMID 40385899, 2025). "For instance, FN1 and SIK3 are associated with spondyloepiphyseal dysplasia, PADI2 is related to sclerosis, ERBB4 is connected to amyotrophic lateral sclerosis (ALS), and B3GNT2 and BACE1 are associated with muscular dystrophy and muscular inflammation, respectively." (PMID 38788487, 2024). "A heterozygous mutation in ERBB4 (c.2136T>G, p.Ile712Met) was also reported in late-onset alS/FTD." (PMID 35481267, 2022). "Interestingly, germline mutations in ERBB4 have also recently been linked to amyotrophic lateral sclerosis and schizophrenia, and the loss of ErbB4 expression is found in patients with relapsing–remitting multiple sclerosis." (PMID 31937769, 2020). "Dominant mutations in ERBB4 have previously been shown to cause amyotrophic lateral sclerosis (OMIM #615515) and therefore represents an attractive candidate gene for neurodegenerative disease in which recessive rare mutations may be linked to PD." (PMID 27640074, 2016). "ERBB4 is related to amyotrophic lateral sclerosis (ALS) in patients with a family history and is thought to cause ALS-19." (PMID 35481267, 2022).
bladder cancer (12 papers, 2004 to 2023). "The ERBB4 abundancy was predicted to be decreased in several cancers, including lung, esophageal, cervical, and bladder carcinoma; however, the ERBB4 expression in OC was suggested to remain high." (PMID 34774079, 2021). "Regarding growth factor receptor genes, treatment with DOX increased some of these genes, such as ErbB2, ErbB4 and FGF2 in the tumors, which are up-regulated in bladder cancers and responsible for disease progression." (PMID 22824624, 2012). "In contrast, several coexpression patterns were independent prognostic indicators of bladder cancer death, namely, EGFR-ErbB2, ErbB2-ErbB3, and high EGFR or ErbB2 plus low ErbB3 or ErbB4." (PMID 22991510, 2012). "No expression of ERBB4 was detected in any of the bladder cancer cell lines or in normal bladder samples." (PMID 21364580, 2011).
lung adenocarcinoma (12 papers, 2007 to 2025). A carcinoma that arises from the lung and is characterized by the presence of malignant glandular epithelial cells. "Results showed that DNA copy number abundances of EGFR, ERBB2, ERBB3, and ERBB4 had associations with overall survival in lung adenocarcinoma with EGFR-activating mutations." (PMID 26824984, 2016). "Afatinib is an irreversible inhibitor of the ERBB receptor family (including EGFR, HER2, ERBB3, and ERBB4), and has been approved for the treatment of advanced lung adenocarcinoma." (PMID 39406703, 2024). "In this study, EGFR-activating mutation status and DNA copy number abundances of EGFR, ERBB2, ERBB3, and ERBB4 were measured in 261 surgically resected lung adenocarcinomas." (PMID 26824984, 2016). "Thus, we hypothesized that ERBB4 functions as a tumor suppressor in the solid type of lung adenocarcinoma." (PMID 33446784, 2021). "We identified several targetable pathways in EGFR/KRAS/ALK-negative lung adenocarcinoma including PI3K/mTOR signaling (TSC1, PIK3CA, AKT2), receptor tyrosine kinase signaling (ERBB4), cell cycle regulation (CHEK2, CDC27), and DNA repair (PARP4)." (PMID 24576404, 2014). "Gene mutations observed differ between lung adenocarcinoma and lung squamous cell carcinoma, with KRAS, EGFR, LPHN3, KEAP1, and TLR4 being relatively common in lung adenocarcinoma, whereas BAI3, FBXW7, GRM8, ERBB4, MUC16, and RUNX1T1 are common in lung squamous cell carcinoma." (PMID 39594843, 2024). "However, a study assessing CNVs in ErbB genes found that half of all lung adenocarcinomas have CNVs of EGFR, ERBB2, ERBB3 and ERBB4, with higher CNV number corresponding to poorer prognosis." (PMID 34274969, 2021). "Trajectory analysis identified ERBB4, SEMA4A, GCNT2 and SOX4 as key factors in AT2 cells that may promote cell proliferation, migration, or epithelial-mesenchymal transition (EMT) during the progression of lung adenocarcinoma (LUAD)." (PMID 41415280, 2025).
bipolar disorder (11 papers, 2009 to 2025). A disorder of the brain that causes unusual shifts in mood, energy, activity levels and the ability to carry out day-to-day tasks. "ErbB4 is active in both the developing and adult brain, and certain people with bipolar disorder have mutations in the gene that codes for the protein." (PMID 30179154, 2018). "For example, the leading candidate risk factor gene, NRG1, which has also been linked to bipolar disorder, is minimally expressed during late adolescence together with its ligand ERBB4." (PMID 19457239, 2009). "Future research should examine whether drugs that target ErbB4 could treat mania and improve the lives of people with bipolar disorder and related conditions." (PMID 30179154, 2018). "Thus, together with KCNQ/M-channels activated by PIP2, ERBB4 takes part in regulation of neuronal excitability, an aspect that could be important in the pathogenesis of bipolar disorder." (PMID 33193575, 2020). "However,recent genome-wide association analyses have not provided evidence for commonvariation in NRG1 or ERBB4 influencingschizophrenia or bipolar disorder susceptibility." (PMID 21637803, 2011).
neuroblastoma (11 papers, 2013 to 2025). Neuroblastoma (NB) is the most common solid, extracranial childhood tumor. "Our group has shown that expression of Her-4/ERBB-4 confers a worse prognosis for neuroblastoma by mediating reduced cell proliferation and anoikis resistance, as well as conferring direct resistance to cisplatin, doxorubicin, and ifosfamide." (PMID 24062983, 2013). "Moreover, recent studies show the implication of ERBB4 in the development and malignant phenotype progression of colon, lung, ovarian, gastrointestinal, melanoma, and neuroblastoma tumors, among others." (PMID 32316671, 2020). "Similarly, we also showed that the NSCLC model acquired hyperactivation of EGFR after exposure to lorlatinib (i.e., H3122-LR100 cell line), whereas the lorlatinib-resistant neuroblastoma cell line GLB-Ga-LR1000 was associated with the hyperactivation of EGFR and ErbB4." (PMID 39767726, 2024). "In neuroblastoma, the ErbB tyrosine kinases, such as EGFR and ERBB4, have been reported to promote cell growth and prevent apoptosis in preclinical models via the MAPK–ERK and PI3K–AKT49–51 pathways." (PMID 40229600, 2025). "We found two ERBB family members, ERBB4 and ERBB3, and P‐gp to be upregulated in resistant neuroblastoma cell lines." (PMID 36181342, 2023). "SK-N-BE neuroblastoma cells, which show high expression of the ErbB4 receptor, were exposed to this CM and NRG3-specific ErbB4 activation was observed after appropriate inmmunoprecipitation and immunoblotting procedures." (PMID 25268740, 2014).
thyroid cancer (10 papers, 2013 to 2024). "Similarly, the enrichment of FGFR3 mutations in salivary gland tumors and ERBB4 mutations in thyroid cancers among Asian patients suggests that clinical investigations targeting these alterations need to target demographically diverse patient communities." (PMID 38297963, 2024). "The HER/ErbB family of receptors including EGFR (HER1/ErbB1), HER2 (ErbB2), HER3 (ErbB3) and HER4 (ErbB4) plays a critical role in tumorigenesis including thyroid cancer." (PMID 27517321, 2016). "Of particular interest are four observed ERBB4 (alias HER4) variants, which have not been connected to this type of thyroid carcinoma so far." (PMID 29133385, 2018). "In addition, in clinical immunohistochemical study, increased expression of HB-EGF and its receptors, HER1 and EGFR4 (HER4/ErbB4), was observed in thyroid carcinoma cells." (PMID 23917679, 2013).
Alzheimer disease (9 papers, 2009 to 2025). A progressive, neurodegenerative disease characterized by loss of function and death of nerve cells in several areas of the brain leading to loss of cognitive function such as memory and language. "A recent study identified ERBB4 signal transduction as an overlapping pathways associated with human aging and Alzheimer’s disease." (PMID 37855863, 2024). "This study aims to identify differentially expressed genes (DEGs) in Alzheimer’s disease and elucidate the relationship between the hub gene ERBB4 and AD using molecular biology, cell biology, and genetic approaches." (PMID 40227858, 2025). "This study aims to identify DEGs in Alzheimer’s disease and elucidate the relationship between the hub gene ERBB4 and AD using molecular biology, cell biology, and genetic approaches." (PMID 40227858, 2025). "Using co-immunofluorescence staining of Alzheimer’s disease brain tissues, we confirmed pathologic downregulation of ERBB4 and transcription factor NFIA in reactive astrocytes." (PMID 37533101, 2023). "Until now, functional analyses of this complex are available only in Embryophyta and Metazoa, where it is known to be involved in the cleavage of Notch and other proteins such as ErbB4 and APP (amyloid precursor protein, implicated in Alzheimers disease)." (PMID 19825158, 2009). "Ablation of NRG3 and ERBB4 leads to a reduction in the number of excitatory synapses on small parvalbumin-positive interneurons, altered short-term neuroplasticity, and disinhibition of the hippocampal network, which plays a critical role in intercellular communication in alzheimer’s disease." (PMID 38383423, 2024).